IL4 (interleukin 4)
Diseases named in the same sentence as IL4 in open-access papers (continued):
Sharing a sentence is not in itself a finding about the gene and the disease.
scleroderma (13 papers, 2005 to 2025). Scleroderma is a rare autoimmune connective tissue disorder characterized by abnormal hardening of the skin and, sometimes, other organs. "Systemic inflammation and increased inflammatory markers such as IL-4 and IL-13 are associated with scleroderma." (PMID 28540270, 2017). "Additionally, therapeutic blockade of IL-4 in a mice model of scleroderma leads to reduced dermal collagen deposition and fibrosis." (PMID 29038604, 2017). "To clarify whether modulation of IL-4 and TGF-β has a role in the prevention of sclerosis induced by HGF gene transfection in the scleroderma model mouse, we examined the mRNA expression of these cytokines." (PMID 17049072, 2006). "The neutralizing antibody SAR156597 for IL-4 and IL-13, which directly induce CCL17, reduced the CCL17 levels in the plasma and exhibited significant improvement in the skin scores and a trend toward improved respiratory function in a phase II study of the multiorgan fibrosing disease scleroderma." (PMID 40269953, 2025). "We found that HUMSCs-Ex elevated M1 macrophage markers (IL-6, IL-12p40, iNOS) and inhibited M2 macrophage markers (IL-4, IL-10, Arg-1 and CD206) in a mouse model of scleroderma, thus suggesting that HUMSCs-Ex might play an antifibrotic role by regulating the M1/M2 macrophage balance." (PMID 34784013, 2022). "Recent studies with BAL in scleroderma patients have shown that a subset of them, who present more than 15% lymphocytes in BAL, or have activated, long-lived CD8+ T cells, or produce type 2 cytokines (IL-4 and IL-5) by the CD8+ TLs, present a more aggressive form of interstitial pneumonia." (PMID 16042790, 2005).
adenoma (12 papers, 2011 to 2025). A neoplasm arising from the epithelium. "In fact in healthy subjects, the sIL-2R in men and sIL-6R in women were principally related to IFNγ, which plays an important role in the development of Th1 cells; in adenoma the TNFα in men and IL-4 in women were, respectively, related to IFNγ and IL-6." (PMID 22235223, 2011). "Moreover, the upregulated Th2 cells, identified by the CCR4 expression in the tissue-derived CD4+T cells, from adenoma to CRC were consistent with the peripheral CD4+IL-4+ Th2 response." (PMID 38343544, 2024). "The overexpression of IL-4 in adenomas, serrated adenomas, and hyperplastic polyps may suggest its role in CRC development." (PMID 35884974, 2022). "However, there were no significant microscopically identifiable differences between the degree of inflammation or types and configuration of adenomas between AOM/DSS-treated mice ± M(IL4) at day 33 or day 54 groups." (PMID 34691050, 2021). "CD4+IL-4+ Th2 cells were increased in the CRC group when compared with those in HPs and adenoma grade I (2.11 vs. 5.63, P = 0.0027; 2.20 vs. 5.63, P = 0.0049)." (PMID 38343544, 2024). "Interleukin-1β, IL-4, and TNF-α are overexpressed in early events of CRC development, such as hyperplastic polyps, adenomas, and serrated adenomas." (PMID 35884974, 2022). "The expression of IL-4, TNF-α, COX-2, and IL-1β is higher in serrated adenomas than in adenomas, but the expression of IL-10 shows the opposite trend." (PMID 35884974, 2022). "Interleukin-4 is overexpressed in early events of CRC development, including hyperplastic polyp, adenoma, and serrated adenomas, whereas in adenocarcinomas, IL-4 levels are not elevated compared with normal mucosa." (PMID 27148488, 2016). "Analysis of TNF-α, CXCL1, IL-1β, IL-10 protein and TGF-β mRNA levels in colonic tissue segments devoid of obvious adenomas revealed the expected increases in these cytokines in the AOM/DSS mice were not affected by M(IL4) treatment." (PMID 34691050, 2021). "Furthermore, cytokines that are known to promote (IL-12, IFN-γ, and IL-2) or regulate (IL-10, IL-4, and IL-17) T-cell polarization and differentiation were similar in the serum of individuals with and without detectable adenomas." (PMID 25884547, 2015). "We assessed the association between plasma endotoxin concentrations, plasma cytokines IL-4, IL-6, IL-8, IL-10, TNF-α, and interferon-γ (IFN-γ) levels, and local cytokine mRNA expression levels of IL-4, IL-6, IL-8, IL-10, IL-17, TNF-α, and IFN-γ in relation to adenomas." (PMID 23442743, 2013).
anaemia (12 papers, 2011 to 2026). "Our results suggest that IL-4 may have a stimulatory effect on the development of iron deficiency anemia in SLE patients." (PMID 38139169, 2023). "Both IFN-γ and IL-4 can cause anemia/hemophagocytosis through different pathways." (PMID 26942577, 2016). "Furthermore, a study discovered that IL-4 was a significant predictor of hemoglobin in children with severe malarial anaemia." (PMID 35820892, 2022). "Comparisons of patients with mild TB and mod-sev disease or anemia, demonstrated that Th1 (IL-2, IFN-γ, and TNF-α) as well as Th2 (IL-4, IL-13, and IL-10) and Th17 responses were higher in mild TB disease." (PMID 38162636, 2023). "Trend analysis of IL-2, IL-5, FGF, PDGF-bb, IL-17, CCL5, IL-4, IL-13, IFN-γ, IL-7 and TGF-β1 uncovered that as the severity of anemia increased, the concentrations of these inflammatory molecules decreased." (PMID 37143662, 2023).
bacteremia (12 papers, 2011 to 2025). "Given our observations of increased intestinal permeability and bacteremia in baso IL-4/IL-13 (−) mice, we assayed plasma MPO and NE, antimicrobial effectors frequently used as markers for neutrophil activation." (PMID 38780542, 2024). "Specifically, basophil-dependent IL-4/IL-13 control MC activation and prevent infection-induced intestinal barrier damage and bacteremia, perhaps via regulation of eosinophils, macrophages, and Th17-mediated inflammation." (PMID 38780542, 2024). "Among the Th-2 cytokines, IL-10 and IL-4 were significantly elevated in candidemia patients compared to healthy controls, but only IL-10 was significantly elevated in candidemia compared to bacteremia groups." (PMID 34684298, 2021). "It was found that the fungal sepsis is associated with substantial increase in all cytokines levels (TNF-α, IL-1β, IL-4, IL-6, and IL-10), when compared with bacterial sepsis." (PMID 28367457, 2017). "Only after the onset of bacteremia were IL-4 levels higher in the acutely infected cats when compared with the CMt recovered cats, and the IL-4 levels were correlated with the bacterial load." (PMID 23216686, 2012). "An initial decrease in the ratio of IL-4/IFN-γ was followed by an increase, which was in turn followed by bacteremia." (PMID 23216686, 2012). "This rarity is attributed to the distinct pathophysiology of parasite-induced systemic inflammation, which typically involves type-2 immune responses (IL-4/IL-5/IL-13 dominance) rather than the cytokine storms characteristic of bacterial sepsis." (PMID 41488892, 2025). "Even though there was an increase in the levels of IL-4 in the candidemia group compared to the bacteremia group, that was statically not significant (p = 0.009)." (PMID 34684298, 2021).
bipolar disorder (12 papers, 2014 to 2024). A disorder of the brain that causes unusual shifts in mood, energy, activity levels and the ability to carry out day-to-day tasks. "More rigorous controlled studies, accounting for medication use and mood state effects need to be done before we can arrive at a better understanding regarding the role of IL-4 in bipolar disorder." (PMID 25202283, 2014). "Additionally, the levels of IL-6, IL-8, TNF-α, and IL-4 were found to increase during the acute manic phase of bipolar disorder." (PMID 38807424, 2024). "Patients with bipolar disorder (BD) showed significantly higher levels of IL-4 than patients with MDD, implying that IL-4 may be a biomarker for differentiating MDD from BD." (PMID 37892657, 2023). "Furthermore, increased serum levels of Interleukin 4 (IL-4) were detected in patients in the manic phase of bipolar disorder." (PMID 37803327, 2023). "One might speculate that IL-4 elevation in bipolar disorder may be of compensatory nature, to buffer against the increase of proinflammatory cytokines seen in the condition." (PMID 25202283, 2014). "The utility of IL-4 as a biomarker of diagnosis for MDD and bipolar disorder has only been examined by two research teams so far." (PMID 38238514, 2024). "Meta-analyses with three or more studies were performed for BDNF, IL-4, TNF-α and IFN-γ in patients with mania and BDNF for bipolar depression." (PMID 30113291, 2018). "A meta-analysis of 30 studies that included 1351 individuals with bipolar disorder and 1248 controls found that plasma/sera levels were elevated for IL-6, TNF-α, soluble IL-2 receptor, IL-4, IL-10, IL-1 receptor antagonist, and soluble TNF receptor-1." (PMID 29803226, 2018). "Levels of IL-2, IL-4, IL-10 and IFN-γ were not significantly different from controls in either mania or euthymia, but current study numbers mean no conclusions can be reached regarding levels in bipolar depression; further studies are required." (PMID 30113291, 2018).
chlamydial infection (12 papers, 2008 to 2025). "Resistance to chlamydial infection is associated with increases in Th1 cytokines, such as IFNγ, which promote cytotoxic T cell responses; conversely, a Th2-dominated response, characterised by increased IL4 and promoted by IL10, is associated with persistence of infection." (PMID 27706211, 2016). "The results suggest that Sema3E can modulate cytokine responses differently by preferentially promoting Th1/Th17 while reducing IL-4/IL-10 responses after chlamydial infection." (PMID 35983029, 2022). "Specifically, we have observed that Sema3E treatment enhances IFN-γ and IL-17 production but reduces IL-10 and IL-4 cytokine response in the lungs and spleen after chlamydial infection." (PMID 35983029, 2022). "In our results, the expression of IL-4 and IL-10 were increased significantly in the coinfection groups, suggesting that chlamydial infection mediated the polarization of Th1/Th2 to the Th2 direction." (PMID 32326284, 2020). "Chlamydial infection in neonatal mice induced increased production of Th2 cytokines (IL-4, 5, 10, and 13) in both BAL and serum, while infected adult mice produced increased Th1 cytokines (IL-2, IFN-γ)." (PMID 24376704, 2013). "Elevated levels of IL-4 and IL-5 in splenic lymphocytes from IFN-γ--/-- mice following chlamydia-specific challenge and the inability in controlling local chlamydial infection and associated tissue damage and cellular infiltration has also been reported." (PMID 19698128, 2009). "While little is known regarding Ag-specific CD4+ T cell (IL-4 and GM-CSF) secretory responses during Chlamydia infection, we show that these T helper cytokines were increased during chlamydial infection." (PMID 18700040, 2008). "The increased expression of GATA-3 and IL-4 secretion of our study favors the dominance of Th2 cells, reflecting the switching of IFN-γ production by Th1 to IL-4 production by Th2 that probably subsequently result in the pathological development of chlamydia genital infection." (PMID 32413046, 2020). "Thus, the IL-4-STAT-6 pathway is perhaps involved in activating and regulating Th2 immune response during CIS and chlamydia genital infection." (PMID 32413046, 2020). "Again, there was no change detected in IL-2, IL-4, IL-12 or IL-17α due to chlamydial infection in any of the mice (data not shown)." (PMID 23189195, 2012). "Chlamydial infection of mice lead to the development of CD4+ T cells that significantly secreted IL-6, IL-10, and GM-CSF, but not IL-4, in response to C. muridarum re-stimulation." (PMID 18700040, 2008).
Cirrhosis (12 papers, 2017 to 2024). A chronic disorder of the liver in which liver tissue becomes scarred and is partially replaced by regenerative nodules and fibrotic tissue resulting in loss of liver function. "A higher trend of pro-inflammatory cytokines including IL-1α, IL-1β, IL-6, IL-8, IFN-γ and TNF-α was detected in the plasma from ACLF patients than that from cirrhosis patients, as well as the anti-inflammatory cytokines including IL-4, IL-10 and IL-13." (PMID 37380987, 2023). "SB reduced the serum concentrations of TNF-α, IL-1β, IL-6, and IL-4 in animals with metabolic dysfunction-associated steatotic liver disease (MASLD); lowered the serum TNF-α and IL-6 levels in experimental cirrhosis in rats; and reduced the CRP levels in decompensated cirrhosis." (PMID 39203520, 2024). "In a rat cirrhosis model, GA prevented an increase in the levels of proinflammatory cytokines (IL-1α and TNFα) in the plasma and the depletion of the anti-inflammatory cytokine IL-4 resulting from chronic bile duct ligation." (PMID 36720896, 2023). "Interferon (IFNγ), IL-4, and IL-17 concentrations were the lowest in patients with HCC with cirrhosis." (PMID 38015590, 2023). "Interestingly, iNKT cells from patients with HCV-related cirrhosis showed a marked increase in the production of pro-fibrotic IL4 and IL13, suggesting that iNKT cell effector functions are modified during progression of chronic viral hepatitis to cirrhosis." (PMID 37006304, 2023). "Additionally, both NAFLD-HCC and NAFLD-cirrhosis BE dampened the production of IL-4 compared to non-NAFLD control BE (P < 0.0001)." (PMID 33420074, 2021).
endotoxemia (12 papers, 2009 to 2024). "IL-6 could induce the expression of the receptor for IL-4 and augment the response to IL-4 in macrophages, but IL-6raΔmyel mice are resistant to IL-4-mediated M2 polarization and exhibit enhanced susceptibility to lipopolysaccharide (LPS)-induced endotoxemia." (PMID 28948005, 2017). "When macrophages are unable to respond to IL-4 and IL-13 cytokine signals in IL4RαLysMCre mice the hosts succumb to endotoxemia, which can be in part rescued by antibiotic treatment." (PMID 30459767, 2018). "Plasma levels of LPS also increased nearly 20-fold and recruitment of eosinophils was dramatically reduced in the intestines, confirming that the acute mortality of Il4−/− mice was due to the increased Th1/NOS2/endotoxemia and reduced Th2 effector response." (PMID 19360123, 2009). "If the host is not able to produce IL-4 alone or IL-4 with IL-13, the mortality rate increases as the eggs are not excreted sufficiently, causing endotoxemia." (PMID 33042153, 2020). "Furthermore, in the absence of IL-4 alone, or both IL-4 and IL-13, there is acute mortality with impaired egg excretion leading to endotoxemia." (PMID 23596444, 2013).
infertile (12 papers, 2009 to 2025). "Low levels of IL-4 and IL-10 are seen in women experiencing spontaneous abortions, recurrent miscarriages and infertility." (PMID 41394354, 2025). "First, women with severe infertility were positioned on their list since the mean ratio of Th1/Th2 (TNFα/IL-4) was greater than the ratio of Th1/Th2 in infertile women and women with IVF failure." (PMID 36937474, 2023). "On stimulation of CD4+ T cells with IncB or IncC, IFN-γ and T-Bet levels were found to be positively correlated in CT-positive fertile women whereas IL-4 mRNA levels were positively correlated to GATA3 expression in CT-positive infertile women." (PMID 19698128, 2009). "In contrast, IL-1β, IL-4, IL-5, IL-6, IL-10 mRNA expression levels were significantly higher (P < 0.05) in cells obtained from CT-positive infertile women compared to controls and CT-positive fertile women." (PMID 19698128, 2009). "Production of IL-4 and IL-10 by NK cells, regulatory B cells, T cells, and others is decreased in women who have had spontaneous abortions, recurrent miscarriages, small for gestational age babies, and infertility." (PMID 24904596, 2014). "The increase in IL-2 and IL-4 production by whole sperm cells-stimulated PBMCs of infertile patients with ASA, as compared to controls, could create the environment that lead to generation of Th2-type of response and resulting in antibody production." (PMID 22952917, 2012). "Significant higher expression (P < 0.05) of Interferon-gamma, IL-12, IL-23 and GM-CSF were found in Inc-stimulated CD4 enriched cervical cells of CT-positive fertile women and contrastingly high IL-1 Beta, IL-4, IL-5, IL-6 and IL-10 levels were found in CT-positive infertile women." (PMID 19698128, 2009). "Overall our data shows that CT IncB and IncC are able to upregulate expression of cytokines, namely interferon-gamma, IL-12, IL-23 and GM-CSF in CT-positive fertile women while expression of IL-1 Beta, IL-4, IL-5, IL-6 and IL-10 were upregulated in CT-positive infertile women." (PMID 19698128, 2009). "Our study is the first study to enrich lymphocytes from the follicular fluid and analyze the expression of IFN-γ, IL-4, IL17A, and IL10 in lymphocyte subsets of PCOS patients with infertility using flow cytometry." (PMID 30988342, 2019). "In this study we detected high levels of IL-1β, IL-6, IL-4, IL-5 and IL-10 in IncB or IncC-stimulated CD4+ T cells in CT-positive infertile women compared to CT-positive fertile women and controls." (PMID 19698128, 2009). "Positive correlation (P < 0.05) was found between Interferon-gamma and T-Bet levels in CT-positive fertile women and IL-4 mRNA and GATA3 levels in CT-positive infertile patients upon IncB and IncC stimulation." (PMID 19698128, 2009). "Recent studies have shown that several cytokines, including IFN-γ, TNF-α, IL-2, IL-4, IL-5, and IL-10, were produced by immunocompetent cells in the blood from PCOS with infertility in vitro, which might be involved in chronic inflammation." (PMID 30988342, 2019). "This study was designed to create an experimental varicocele model by asimple surgical procedure in dog with minimum invasion and to investigate the effect ofvaricocele-induced infertility on the expression of six related genes (HSP90, HSP70, IL-4, TNF, KITLG and KIT receptor)." (PMID 28868836, 2017).
oral cancer (12 papers, 2013 to 2023). "The IL-4 -590 SNP is a transition (C → T) that has been associated with oral cancer and is a suitable genetic marker for screening for this condition." (PMID 27220278, 2016). "In addition, some scientists assessed the relationship between IL-4 promoter and IL-6 functional genetic polymorphisms in Asian Indians and tobacco-related oral cancer." (PMID 31582940, 2019). "Functional polymorphisms affecting gene expression of IL-4,-6,-8,-10 and TNF have been shown to strongly associate with increased risk for oral cancer." (PMID 35844493, 2022). "Previous studies showed associations of increased risk for oral cancer with TNF-β polymorphisms genes and increased expression of salivary IL-4 and IL-13." (PMID 31973090, 2020). "Nevertheless, recent studies indicate a correlation of the IL-4 gene but not the IL-1 beta gene polymorphism with oral cancer." (PMID 36497491, 2022). "Among the cytokines that may be involved in oral cancer, interleukins seem to have a crucial function, the most studied being IL-4, IL-6, IL-8, and IL-10." (PMID 30539028, 2018). "Moreover, it seems that IL-4 may inhibit the invasion in oral cancers by decreasing matrix-metalloproteinase- (MMP-) 9 expression." (PMID 30539028, 2018). "The tobacco-related oral cancer is likely to be connected with multiple systemic immune impairs, especially defected CD4+ and CD3+ T cells and a differential regulation of IL-4 and IL-2 in CD8+ and CD4+ T-cell subsets in the peripheral blood." (PMID 31582940, 2019).